TIGIT (T cell immunoreceptor with Ig and ITIM domains)
Diseases named in the same sentence as TIGIT in open-access papers (continued):
Sharing a sentence is not in itself a finding about the gene and the disease.
viral infections (continued). "Additionally, murine models have demonstrated signaling through TIGIT is critical for maintaining chronic exhaustion during prolonged viral infection." (PMID 30959825, 2019). "It has been clearly shown that TIGIT plays critical roles to control viral infection in vivo." (PMID 26735971, 2016). "It has been reported that TIGIT plays critical roles to control viral infection." (PMID 26735971, 2016). "Therefore, we speculated that TIGIT might be involved in regulating perforin-dependent tissue damage following acute virus infection." (PMID 32152316, 2020). "Vice versa we could verify that TIGIT blockade leads to the diminished expression of IL-10 by CD8+ T cells during chronic infection, which indicates that TIGIT is involved in shifting the cytokine balance toward a more IL-10 dominated immune response in the context of viral infections." (PMID 32152316, 2020). "Expression levels of the inhibitory receptor, T cell immunoglobulin and ITIM domain (TIGIT), the co-stimulatory receptor CD226 and their ligand PVR are altered in viral infections and cancer." (PMID 28084312, 2017). "In viral infections, TIGIT alone does not affect viral control but has been shown to limit tissue pathology." (PMID 41094201, 2025). "Specifically, after viral infection, TIGIT directly drives expression of the tissue growth factor amphiregulin (Areg), which is strongly reduced in the absence of TIGIT." (PMID 41094201, 2025). "In this study, the upregulated expression of CTLA-4, LAG-3, 2B4, and TIGIT were observed in CD8+ T cells and CD4+ T cells of mice infected with FMDV, which would inhibit T-cell proliferation and promote T-cell apoptosis during virus infections." (PMID 34960627, 2021). "Thus, despite the high transcriptional repair score observed in CD8+ T cells, TIGIT expression in this subset does not contribute, directly or indirectly, to tissue protection during viral infection." (PMID 41094201, 2025). "Thus, we concluded that in the context of systemic viral infection, TIGIT expression on CD8+ T cells does not equip them with a specific repair function." (PMID 41094201, 2025). "However, co-culture of pNK with OC significantly reduced the expression of DNAM-1 (p = 0.04) and enhanced the expression of TIGIT (p < 0.0001) compared to conditioned-medium, independent of virus infection." (PMID 32195317, 2020).
lung adenocarcinoma (20 papers, 2019 to 2026). A carcinoma that arises from the lung and is characterized by the presence of malignant glandular epithelial cells. "CD155 and TIGIT were correlated with clinicopathological features in lung adenocarcinoma, in which CD155 expression was strongly associated with tumor staging and poor OS." (PMID 35656508, 2022). "The association of the co-expression of TIGIT and CD155 with an unfavorable disease course in lung adenocarcinoma has been shown and with primary squamous cell carcinoma of the esophagus." (PMID 36140182, 2022). "We performed immunohistochemical staining of 84 tumor segments from 22 resected tumor samples to evaluate the expression of PD-L1, PD-1, Nectin-2, PVR, and TIGIT in distinct growth patterns of lung adenocarcinoma." (PMID 34102454, 2021). "CD113 is also frequently found in lung adenocarcinoma (25%) and only represents a deleterious prognostic factor when not co-localized with E-cadherin in cell membrane, likely allowing its binding with nectin-5 or TIGIT to promote cancer progression." (PMID 39267111, 2024). "Additionally, high TIGIT levels are linked to greater severity in lung adenocarcinoma, and patients with overexpressed CD155 in lung adenocarcinoma and SCLC have shorter progression-free survival and overall survival." (PMID 39726592, 2024). "However, the expression profile and functional significance of TIGIT in the immune microenvironment of lung adenocarcinoma (LUAD) remain elusive." (PMID 38279870, 2024). "In recent years, TIGIT has been investigated as an important checkpoint in cancer research focused on esophageal small cell carcinoma and lung adenocarcinoma, where TIGIT-positive patients showed a shorter OS and a lower PFS than those of TIGIT-negative patients." (PMID 38404571, 2024). "TIGIT expression was also documented on tumor cells, especially in cutaneous melanoma, choroidal melanoma, thyroid cancer, undifferentiated pleomorphic sarcoma, lung adenocarcinoma, and esophageal cancer." (PMID 37109579, 2023). "In this study, we propose the use of anti-PD1 and anti-TIGIT checkpoint inhibitors in conjunction with our novel RadScopal technique to battle highly metastatic lung adenocarcinoma tumors, bilaterally established in 129Sv/Ev mice, to mimic high-tumor-burden settings." (PMID 35008385, 2022). "Therefore, to our best knowledge, our study is the first one to show the expression of TIGIT on human lung adenocarcinoma tumor cells." (PMID 34102454, 2021). "Therefore, we aimed to conduct a comprehensive analysis of the co-expression patterns of PD1, LAG3, TIGIT, and TIM3, their prognostic significance, and their association with tumor transcriptomics in patients with advanced lung adenocarcinoma undergoing treatment with PD1/PD-L1 inhibitors." (PMID 39591972, 2024). "In several tumor entities, including lung adenocarcinoma, the expression of this regulatory receptor was found to be increased on TILs, giving tumor cells an additional option to escape the immune system in suppressing the functions of the TILs, when TIGIT binds one of its ligands Nectin-2 or PVR." (PMID 34102454, 2021). "In lung adenocarcinoma, YTHDF1 is significantly negatively correlated with PD-L1, PD-1, PD-L2, CTLA-4, TIGIT, VISTA, and TIM3." (PMID 36479088, 2022).
rheumatoid arthritis (20 papers, 2018 to 2026). A chronic, systemic autoimmune disorder characterized by inflammation in the synovial membranes and articular surfaces. "It is particularly noteworthy that expression levels of CD48 and TIGIT were significantly lower in patients with rheumatoid arthritis compared to those with pSS." (PMID 41476962, 2025). "For instance, a reduction in CD4+ T cells expressing TIGIT has also been observed in rheumatoid arthritis and psoriasis." (PMID 33995373, 2021). "In lymphocyte-dense compartments, such as areas of lymphocytic infiltration in IgG4 pancreatitis or rheumatoid arthritis, levels of TIGIT and PD-1 were higher than in areas containing fewer and scattered lymphocytes." (PMID 30733837, 2019). "Despite recent development of PD-1 agonists in rheumatoid arthritis (RA), little is known about PD-1 and TIGIT coexpression in RA and other immune-mediated inflammatory diseases (IMIDs)." (PMID 42161414, 2026). "Overexpression of TIGIT suppressed CD4+ T cells and ameliorated the severity of rheumatoid arthritis in mouse models." (PMID 35844584, 2022). "Flow cytometry revealed T cell infiltration in the rheumatoid arthritis synovium with differential expression of PD-1, CD45RO, ICOS, TIGIT and CD38." (PMID 36270740, 2022). "Furthermore, we show that CD69+FoxP3+ and TIGIT+FoxP3+ Treg subsets are induced by VD3-primed DCs, which are especially beneficial for the targeted suppression of pathogenic Th17 cell responses that contribute to disease progression in psoriasis and rheumatoid arthritis, among others." (PMID 35874744, 2022). "This CD4− cluster largely expressed Foxp3, Helios, and TIGIT as well as CD25, CD39, CTLA-4, CD71, HLA-DR, and low CD127, thus mirroring CD8+ Treg-like cells which have been described in inflamed joints of rheumatoid arthritis (RA), psoriatic arthritis (PsA), and spondylarthritis." (PMID 39101538, 2024).
lymphoma (19 papers, 2018 to 2025). A malignant (clonal) proliferation of B- lymphocytes or T- lymphocytes which involves the lymph nodes, bone marrow and/or extranodal sites. "Other T cell checkpoints (LAG-3, TIM-3, TIGIT) have been associated with lymphoma progression but clinical data on therapeutic targeting of these checkpoints are not available yet." (PMID 38322418, 2024). "PD-1H KD & PD-1/TIGIT KO anti-CD19 CAR T cells increased the survival of mice with lymphoma or acute lymphoblastic leukemia (ALL)." (PMID 41354926, 2025). "While the TIGIT inhibitory ligand CD155 can be expressed in normal B cells, its expression in lymphoma B cells in associating with infiltrating TIGIT+ T cells has not been deeply investigated." (PMID 35071240, 2021). "Similar results were seen in an A20 lymphoma mouse model which showed coexpression of PD-1 and TIGIT, and near complete disappearance of tumor was seen when mice were treated with both anti-PD-1 and anti-TIGIT antibodies." (PMID 33294467, 2020). "Based on these preclinical data, anti-TIGIT mAbs are being investigated in several phase 1/2 clinical trials, either as monotherapy or in combination with anti-PD-1/PD-L1 Abs or chemotherapy, for the treatment of malignant lymphoma and MM." (PMID 39531203, 2025). "Similarly, a pre-clinical model showing combination of PD-1 and TIGIT blockade having synergistic effect in eliminating lymphoma cells has been reported." (PMID 38322418, 2024). "They found circulating CAR T cells to express higher TIGIT levels in non-responders, and could validate the relevance of this finding in an in-vivo model in which TIGIT blockade led to longer survival of mice challenged with lymphoma cells and CAR T cells." (PMID 38884110, 2024). "Besides, TIGIT/PD-1 dual blockade has remarkably improved anti-tumoral immune responses and promoted tumor rejection in lymphoma animal models." (PMID 34638729, 2021). "It has been described that MCL exhibits features of exhaustion, including high expression of PD-1 and TIGIT in both CD4 and CD8 T cells, as well as the presence of the corresponding ligands PD-L1, CD155 and CD112 in lymphoma cells and/or macrophages." (PMID 37031299, 2023). "HLX301 is a bispecific antibody to PD-L1 and TIGIT being evaluated in a Phase I study for advanced solid tumors and lymphomas (NCT05390528), while HLX53 is an anti-TIGIT Fc fusion protein also being investigated in solid tumors and lymphomas." (PMID 37920162, 2023). "Therefore, it would be of interest to study expression of immune checkpoint receptors like PD1, TIGIT or NKG2A, exhaustion markers, and the functionality of lymphocytes and monocytes in patients with r/r lymphoma in comparison to patients in remission." (PMID 35794135, 2022).
osteosarcoma (19 papers, 2020 to 2026). A usually aggressive malignant bone-forming mesenchymal neoplasm, predominantly affecting adolescents and young adults. "Experimentally, overexpression of SNORA12 in osteosarcoma cells and primary NK cells significantly upregulated TIGIT at both the mRNA and protein levels, while SNORA12 knockdown in NK92 cells reduced TIGIT expression." (PMID 41898368, 2026). "Tiragolumab, an anti-TIGIT antibody, has shown promise when combined with PD-L1 blockade in non-small cell lung cancer and is currently being investigated in osteosarcoma." (PMID 40170852, 2025). "T cells are essential in osteosarcoma, and blocking TIGIT enhances the cytotoxic effects of CD3+ T cells within the TIGIT+ cell-rich microenvironment." (PMID 40570022, 2025). "In this context, the immunoregulatory NECTIN2-TIGIT interaction between osteosarcoma and CD8+ T cells induces TIGIT-mediated T-cell suppression by impairing CD8+ T-cell proliferation and activation." (PMID 39359731, 2024). "Concomitantly, C5/IL7-CAR-T cells in the osteosarcoma microenvironment displayed low TIGIT expression and were able to express more IFN-γ in the NSG mouse model." (PMID 39450160, 2024). "Next, we analyzed the therapeutic potential of blocking TIGIT on NK92 cells to improve their cytotoxic activity against osteosarcoma cells." (PMID 38791381, 2024). "This dysfunctional subpopulation was also evident in advanced osteosarcoma lesions, marked by an elevated expression of T-cell exhausted inhibitory receptors (TIGIT and LAG3)." (PMID 39359731, 2024). "The expression of PVRL2 and PVR by osteosarcoma cell lines add more complexity to the TIGIT/CD226 signaling network." (PMID 38791381, 2024). "The abundant expression of TIGIT in Tregs is consistent with a previous study that identified TIGIT as widely present in various TIL subsets but most abundant in the Tregs of osteosarcoma." (PMID 39359731, 2024). "They found that TIGIT blockade enhanced the cytotoxicity effects of primary CD3+ T cells with a high proportion of TIGIT+ cells against osteosarcoma." (PMID 35515114, 2022). "This study found that macrophage M1 was positively correlated with immune checkpoints PDCD1, CD274 (PD-L1), PDCD1LG2, CTLA4, and TIGIT, suggesting the opportunity of ICBs therapy in osteosarcoma patients with high infiltrating macrophage M1." (PMID 34335756, 2021). "As a target tumor model, we used the osteosarcoma cell line Saos2/143 that naturally express the ligands for TIGIT (CD155/PVR) but also other inhibitory receptors, such as PD-L1." (PMID 34112738, 2021). "It was found that there was a significant relationship of the risk score with important immune checkpoints expressions (CTLA4, PDL1, TIM3, LAG3, TIGIT) in osteosarcoma patients." (PMID 34335109, 2021). "In advanced osteosarcoma, TIGIT+ T cells are highly present supporting the potential clinical application of TIGIT blockade in this tumor." (PMID 34572932, 2021). "In preclinical models of osteosarcoma, blocking TIGIT has been shown to enhance NK cell-mediated cytotoxicity, suggesting that targeting TIGIT could improve the anti-tumor immune response." (PMID 40170852, 2025). "Importantly, using scRNA-seq to analyze samples of cervical cancer and osteosarcoma revealed that blocking TIGIT therapy significantly inhibited tumor cell expansion." (PMID 38649887, 2024). "Notably, TIGIT blockade therapy effectively inhibited OC metastasis in mouse models, consistent with osteosarcoma." (PMID 38649887, 2024). "In osteosarcoma, TIGIT+ T cells are highly present and, when treated ex vivo with an anti-TIGIT antibody, acquire cytotoxic activity against neoplastic cells in vitro, thus supporting the potential clinical application of TIGIT blockade for children affected by this cancer." (PMID 33920505, 2021). "Importantly, TIGIT blockade enhances the cytotoxicity effects of the primary CD3+ T cells with high proportion of TIGIT+ cells against osteosarcoma." (PMID 33303760, 2020).
osteosarcoma (continued). "The study of the heterogeneity and immunosuppressive function of Tregs in naïve primary osteosarcoma demonstrated greater Treg infiltration than in normal bone, with a positive expression of FOXP3, CD4, CTLA-4, and TIGIT in Tregs." (PMID 39359731, 2024). "Blocking the expression of TIGIT can enhance the killing effect of primitive CD3+ T cells, as there is a high proportion TIGIT+ cells in osteosarcoma." (PMID 34895349, 2021). "However, newer checkpoint molecules such as LAG-3, TIM-3, T cell immunoreceptor with Ig and ITIM domains (TIGIT), V-domain Ig suppressor of T cell activation (VISTA), and B7-H3 (CD276) have gained increasing attention as potential targets in osteosarcoma." (PMID 40170852, 2025). "In addition, specific immune checkpoint inhibitors are being explored as new immunotherapeutic strategies for osteosarcoma, such as CTLA-4, LAG3, TIGIT, and PD-1/L1 (Wang S.-D." (PMID 34899864, 2021).
head and neck squamous cell carcinoma (18 papers, 2020 to 2026). A squamous cell carcinoma that arises from any of the following anatomic sites: lip and oral cavity, nasal cavity, paranasal sinuses, pharynx, larynx, and salivary glands. "In mice, blocking the TIGIT/CD155 axis suppresses the progression of head and neck squamous cell carcinoma." (PMID 35770416, 2023). "Anti-TIGIT treatments demonstrated efficacy in preclinical trials of multiple myeloma and head and neck squamous cell carcinoma (HNSCC) by decreasing tumor progression in a CD8+ T cell-dependent manner." (PMID 35345849, 2022). "Currently, CD155/TIGIT has shown potential targeted therapeutic effects in a variety of malignancies, such as high-grade serous ovarian cancer and head and neck squamous cell carcinoma." (PMID 35433470, 2022). "Cholangiocarcinoma and head and neck squamous cell carcinoma, including oral cancer, pharyngeal cancer and laryngeal cancer, exhibit an inhibitory immune microenvironment, in which TIGIT is positively expressed, suggesting that targeting TIGIT may be with a promising application prospect." (PMID 35433470, 2022). "In Head and Neck Squamous Cell Carcinoma (HNSCC), both in vitro and in vivo blockade of TIGIT increased antitumor immune responses." (PMID 41596586, 2026). "For instance, in the model of the head and neck squamous cell carcinoma, anti-PD-L1 treatment in vivo resulted in increased CD155 expression on MDSCs and, interestingly, vice versa, the blockade of TIGIT resulted in the upregulation of PD-L1 expression." (PMID 37444427, 2023). "In head and neck squamous cell carcinoma (HNSCC), CD155 expression on MDSCs promoted MDSCs-mediated T-cell suppression, and in vitro blocking the TIGIT/CD155 pathway with anti-TIGIT antibodies substantially inhibited MDSCs immunosuppressive capacity and enhanced the antitumor immune response." (PMID 38609997, 2024). "Interestingly, blocking PD1/PD-L1 signaling was shown to increase the expression of TIGIT on Tregs in head and neck squamous cell carcinoma (HNSCC) patients, suggesting a resistant mechanism for αPD1 immunotherapy mediated by TIGIT." (PMID 34025646, 2021). "Moreover, TIGIT blockade presents anti-tumor efficacy in Tgfbr1/Pten2 conditional knock-out (KO) mouse model that spontaneously develops head and neck squamous cell carcinoma (HNSCC) upon tamoxifen injection." (PMID 33670993, 2021).